ALK (ALK receptor tyrosine kinase)
Diseases named in the same sentence as ALK in open-access papers (continued):
Sharing a sentence is not in itself a finding about the gene and the disease.
cancer (1,249 papers, 2006 to 2026). A tumor composed of atypical neoplastic, often pleomorphic cells that invade other tissues. "In conclusion, ALK mutation is associated with promoted cancer immunity and can be treated as a biomarker for favorable outcomes in pan-cancer immune checkpoint blockade." (PMID 41716637, 2025). "An important factor in NSCLC carcinogenesis is Anaplastic Lymphoma Kinase (ALK) fusion mutation, which is often associated with accelerated cancer progression." (PMID 40211955, 2025). "Using the SIFT and Polyphen-2 algorithms, we identified 53 deleterious ALK mutations associated with different newly recognized cancer types." (PMID 40606598, 2025). "Although further research is needed, triple combination comprising ALK‐TKI plus GPX4 inhibitor plus a TKI corresponding to the bypass pathway would be helpful to eliminate the cancer cells and reduce the risk of DTP induction." (PMID 39369284, 2025). "In conclusion, our study identified novel amino acid substitutions in the ALK tyrosine kinase domain associated with cancers beyond hematological malignancies and NSCLC." (PMID 40606598, 2025). "In malignant tumors, ALK mutations or chromosomal rearrangements result in the aberrant activation of ALK and its downstream signaling cascades, with the mitogen-activated protein kinase (MAPK) pathway serving as a critical downstream effector." (PMID 40416876, 2025). "Amino acid point mutations in the ALK protein are critical in conferring resistance to ALK inhibitor therapies in cancer." (PMID 40606598, 2025). "Despite their high risk for BMs, EGFR- and ALK-mutated cancers collectively represent only 17% of the NSCLC population." (PMID 40149325, 2025). "This research underscores the importance of repurposing in silico drugs and highlights the need for continued exploration of ALK mutations in cancer therapeutics." (PMID 40606598, 2025). "Mutations or rearrangements of the ALK gene lead to aberrant kinase activation, driving tumorigenesis in various cancers." (PMID 40872599, 2025). "The pattern of sensitivity was notable in cancer cell lines with ALK fusions, mutations, and amplifications." (PMID 39900433, 2025). "Despite the low number of patients, our work uncovered potential associations between certain cancer-immunity relevant genes and clinical features of ALK-positive ALCL patients." (PMID 41469691, 2025). "In conclusion, the diverse mechanisms of resistance and intricate signaling pathways associated with ALK+ cancers, particularly in NSCLC and other malignancies, reveal the complexity of targeting ALK alterations." (PMID 38397899, 2024). "Lorlatinib-resistant cancers had 11% ALK mutations (including G1202R/G1269A) and two potential bypass mutations." (PMID 38397899, 2024). "Crizotinib has been approved by the FDA for use in malignant tumors with anaplastic lymphoma kinase (ALK) mutations." (PMID 38803433, 2024). "Despite the introduction of newer and newer generations of AKL TKIs, the primary cause of treatment failure in ALK + patients is cancer progression caused by the generation of various resistance mechanisms." (PMID 39457620, 2024). "ALK rearrangement often serves as a driver mutation in cancers, inducing oncogenic hyperactivation of cytoplasmic tyrosine kinase activity irrespective of the fusion partners involved." (PMID 39667359, 2024). "Nonetheless, despite these improvements, the emergence of cancers with compound resistance mutations poses a challenge, indicating the necessity for developing multiple ALK inhibitors targeting various compound mutations." (PMID 38397899, 2024). "Ceritinib-resistant cancers exhibited 22% ALK mutations (including G1128A, G1202R, G1269A, I1171T/E1210K) and similar bypass mutations." (PMID 38397899, 2024). "In several cancers, structural ALK rearrangements whereby the kinase domain-encoding region at the 3’end is fused to various partner genes located at the 5’end have been identified as key oncogenic drivers." (PMID 38835344, 2024).
cancer (continued). "ALK, a promising drug target for multiple cancers, is closely associated with the occurrence and development of cancers." (PMID 38606358, 2024). "Anaplastic lymphoma kinase (ALK) is associated with the tumorigenesis of human cancers, including GBM tumors." (PMID 39055895, 2024). "Among cancers resistant to crizotinib, 16% displayed ALK mutations (such as L1196M, I1171T, D1203N, G1269A/F1174L) and three potential bypass mutations." (PMID 38397899, 2024). "Targeted therapies are designed to specifically interact with molecular alterations—such as mutations in EGFR and ALK genes—that promote cancer cell growth and survival." (PMID 39682234, 2024). "Although similar mutations in other cancers, such as ALK, EGFR, and KRAS in lung cancer or BRAF in melanoma, have revolutionized cancer treatment, identifying analogous markers in GBC is challenging due to its genetic heterogeneity." (PMID 39683528, 2024). "Upon transformation of cancer cells into different histologic subtypes, the loss of driver mutations leading to oncogenesis results in ALK-independent resistance." (PMID 38835344, 2024). "By contrast, the majority of mutations in the ALK gene occur as translocations with a partner gene, resulting in a fusion oncogene, which is subsequently overexpressed in cancers." (PMID 39751645, 2024). "Alectinib-resistant cancers showed 17% ALK mutations (including G1202R, W1295C, G1202R/L1196M) and one potential bypass mutation." (PMID 38397899, 2024). "Targeted therapies are also now FDA-approved in the adjuvant setting for EGFR-mutated cancers and ALK-mutated cancers per the ADAURA, LAURA, and ALINA trials." (PMID 39518093, 2024). "Eventually, preclinical and animal studies support its efficacy against cancers harboring ALK mutations, indicating its potential as a therapeutic agent." (PMID 38397899, 2024). "While the median life expectancy of patients with metastatic LC was below one year just two decades ago, this estimate currently exceeds 3 years for subjects with EGFR-mutated disease and approaches more than 7 years for ALK-driven carcinomas." (PMID 38966170, 2024). "Evidences from genetic manipulation studies show GSTP1 facilitates cell viability and increases resistance to cisplatin and targeted therapy including gefitinib, erlotinib, or afatinib for the relevant EGFR mutated, and crizotinib for ALK translocated cancers." (PMID 36709476, 2023). "Aberrantly formed ALK oncogenes, mainly caused by fusion mutations, ALK gain-of-function mutations, or ALK amplification, have been identified in various cancers." (PMID 37120571, 2023). "Deletions in or near prominent cancer-associated genes (for example, ALK, LIN28B, PDGFD and WNT7B) were also detected." (PMID 37188965, 2023). "Anaplastic lymphoma kinase (ALK) is a receptor tyrosine kinase implicated in several types of cancer." (PMID 37175956, 2023). "ALK immunoreactivity was also significantly associated with expression of cancer stem cell (CSC)-related molecules (cytoplasmic CD133, ALDH1, Sox2) and neuroendocrine markers (CD56 and synaptophysin)." (PMID 37592266, 2023). "Lorlatinib demonstrates high potency across acquired ALK-activating mutations in adult cancers, including the intractable ALK variants (F1174L and F1245C) found de novo in neuroblastoma." (PMID 37012551, 2023). "The development of cancer through ALK receptor signaling can be initiated by either an ALK fusion protein or a point mutation in the full-length ALK receptor." (PMID 37892172, 2023). "The aim is to determine the efficacy of alectinib for ALK-positive rare cancers in adults, children, and adolescents/young adults as well as for common cancers in which ALK mutation or amplification is considered infrequent." (PMID 37656266, 2023). "One potential strategy to boost the immune response to these cancers would be to vaccinate patients with DNA encoding EGFR or ALK, or peptides taken from the sequences of the proteins they encode." (PMID 37795653, 2023).
cancer (continued). "The anaplastic lymphoma kinase (ALK) gene encodes a receptor tyrosine kinase that is commonly hyperactivated in several cancers through chromosomal translocations or activating point mutations." (PMID 38032104, 2023). "The proposed CODRP algorithm better discriminates ALK-targeted drug responses according to ALK mutations by considering multi-parameters (cancer stage, cell growth rate)." (PMID 37993887, 2023). "EGFR TKIs have a high response rate (60%–70%) in EGFR-mutated cancers, while Anaplastic Lymphoma Kinase (ALK) inhibitors have a comparable response rate (60%) in patients with ALK translocations." (PMID 38186568, 2023). "Finding BRAF mutations or PPARG, NTRK1, NTRK3 and ALK fusions were strong predictors of a higher risk of cancer (approaching 100%) while other mutations like RAS, PTEN and EIF1AX or THADA fusions were associated with a significant but lower risk of cancer." (PMID 37510219, 2023). "Expectedly, ALK is thus a prominent target in cancers where its dysregulation is linked to oncogenesis." (PMID 36991452, 2023). "In Em Ca cell lines, full-length ALK overexpression increased proliferation, decreased susceptibility to apoptosis, enhanced cancer stem cell features, and accelerated cell mobility, whereas these phenotypes were abrogated in ALK-knockdown cells." (PMID 37592266, 2023). "Though efficacious against ALK-positive cancers, crizotinib is incapable of blocking mutated ALK, a problem relentlessly haunting the first and second generations of ALK inhibitors." (PMID 37175956, 2023). "B3 demonstrated activity against cancer cells with mutated ALK (L1196M and G1202R) conferring resistance to crizotinib." (PMID 36986673, 2023). "When treated to ALK-positive NSCLC cells, the Cer/Pom-PEG@GNPs effectively degraded ALKs and induced ALK deficiency-related cancer cell death." (PMID 36839734, 2023). "Pathogenic variants in five “other” cancer predisposition genes (ALK, BUB1B, FANCG, RB1 and XPC) exclusively investigated for truncating variants, were identified in seven patients." (PMID 35039564, 2022). "Nonsynonymous mutations were also identified in 51 additional cancer genes in single primary ileal NETs and metastases, including ALK, DAXX, KRAS, and MEN1." (PMID 35922826, 2022). "After treatment with lorlatinib or sequential treatment with ALK-i, compound ALK mutations have been detected in patients that developed resistance, adding complexity to the spectrum of detectable cancer cell subpopulations." (PMID 36230686, 2022). "No clear consensus sequences were found around the breakpoints of the ALK gene across different cancer types or fusion variants." (PMID 36369474, 2022). "The translocation and fusion of echinoderm microtubule-associated protein-like 4 (EML4) and anaplastic lymphoma kinase (ALK) have been implicated in various cancers." (PMID 36303815, 2022). "In fact, when patients receive sequential ALK-i treatment, cancer cells accumulate more than one resistance mutation, increasing intercellular genomic heterogeneity." (PMID 36230686, 2022). "In this study, we sought to determine the potential impact of P-gp and ABCG2 on the susceptibility of human cancer cells to the second-generation ALK inhibitor ensartinib." (PMID 35565470, 2022). "Since then, fusions, mutations, and alternative splicing of ALK have been successively detected in other cancers, such as NSCLC, digestive tract cancer, renal cell carcinoma, breast cancer, thyroid cancer, and ovarian cancer, among others." (PMID 36591504, 2022). "From the current studies, it can be perceived that old age is a risk factor for various cancers and decreases cardiac function, but no clinical study has shown sex differences in cardiac disorders caused by ALK-TKIs." (PMID 35370632, 2022). "ALK is a promising neoantigen that can be applied in the development of ALK mutated cancer vaccines because ALK mutations can trigger the body’s T cell response." (PMID 36591504, 2022).
cancer (continued). "Experiments in mice showed that ceritinib is active against cancers derived from patients who have acquired resistance to crizotinib and is effective against ALK-positive cancers with resistance mutations of L1196M and G1269A." (PMID 35727390, 2022). "Brigatinib (BGT) is a second-generation anaplastic lymphoma kinase (ALK) inhibitor that is used to treat a certain type of non-small cell lung cancer (NSCLC) by inhibiting an abnormal protein that causes cancer cells to multiply." (PMID 35337145, 2022). "An increase in cancer cell apoptosis has been observed but only in cells with amplified ALK or ALK gain-of-function mutations such as the NBL hotspot mutations." (PMID 34575503, 2021). "(2015) found that treatment with kinase inhibitors against BRAF, ALK (anaplastic lymphoma kinase) or EGFR mutations significantly modulates the secretome of drug‐sensitive cancer cells." (PMID 34137158, 2021). "ALK gene fusion copy number gain, as well as different oncogenic driver mutations that emerge independently, constitute alternative pathways for cancer cells to develop ALK inhibitor resistance." (PMID 33572278, 2021). "We here find that EML4–ALK variant 1 (exon 1–13 of EML4 fused to exon 20–29 of ALK) forms condensates via phase separation in the cytoplasm of various human cancer cell lines." (PMID 33976114, 2021). "The heterogeneous profile of cancer-related gene mutations in the same patient showed the near elimination of an initial ALK R1275Q mutated clone after therapy, further corroborating the extensive temporal heterogeneity." (PMID 34815394, 2021). "Previous studies have revealed that genomic rearrangement is highly associated with SE abnormality in cancers, and thus we focused on the most frequent fused oncogene ALK in LUAD." (PMID 34001209, 2021). "Crizotinib showed satisfactory results in some paediatric cancers carrying gain-of-function ALK mutation." (PMID 34884690, 2021). "Ba/F3 cell lines were used, and they either expressed wild type EML4-ALK as a model of ALK-TKI-naïve cancer, or else mutant EML4-ALK with one ALK resistance mutation, mimicking resistance following first- or second-generation ALK inhibitor treatment." (PMID 33572278, 2021). "ALK was first identified in cancers where chromosomal rearrangements caused the fusion of its intracellular domain with other proteins." (PMID 34020009, 2021). "Previous reports revealed that secondary mutations in the ALK kinase domain such as I1171T/N/S, V1180L, G1202R, and L1196M emerged in patients with alectinib-resistant cancer." (PMID 33627640, 2021). "In various cancers, other aberrant ALK forms and aberrant ALK expression are generally caused by at least one of four alterations in the ALK gene mechanisms: mutations, gain-of-function mutations, amplification, or translocations." (PMID 33466277, 2021). "Around 3–7% of NSCLC cases present active ALK rearrangement (ALK+ NSCLC) that produces an abnormal activity of the ALK protein cell signaling pathway and causes the cancer cells to grow and metastasize." (PMID 33659043, 2021). "It has been reported that lorlatinib is effective in cancers harboring mutations in ALK that conferred resistance to ALK inhibitors, including G1202R and I1171N mutations." (PMID 34359604, 2021). "Since then, fusions, mutations, and alternative splicing of ALK has been detected in several cancers including NSCLC, renal cell carcinoma, thyroid cancer, digestive tract cancer, breast cancer, ovarian carcinoma and leukemia." (PMID 33806977, 2021). "Cancers harboring rearrangements in the ALK gene are susceptible to treatment with tyrosine kinase inhibitors (TKIs), which inhibit downstream signaling pathways, binding to receptor tyrosine kinases." (PMID 33352844, 2020). "Crizotinib is a first-line chemical approved for the treatment of NSCLC and other cancers with ALK and ROS1 mutations or c-MET amplification 2-5." (PMID 32792859, 2020).
cancer (continued). "Some of the reported mechanisms underlying the acquired resistance to crizotinib in ALK translocated cancers involve secondary mutations, ALK amplification, KIT amplification, and autophosphorylation of epidermal growth factor receptor (EGFR)." (PMID 32133282, 2020). "Most cancer-associated rearrangements in the ALK gene are associated with fusions, copy-gain number, or activating ALK mutations." (PMID 32312912, 2020). "Some of these activating mutations also confer secondary resistance against ALK-TKI in ALK-rearranged cancers." (PMID 32300555, 2020). "With the ProTECT bioinformatics approach, it is possible that more ALK epitopes/peptides can be developed into therapeutic vaccines even for other cancers bearing likely immunogenic ALK mutations." (PMID 32059449, 2020). "With the sequential ALK inhibitors treatment, cancer cells accumulate new mutations in addition to mutations acquired previously." (PMID 31943796, 2020). "Genetic alteration of ALK, including gene amplification, gene fusion, and mutation with gain of function, has been identified in different cancers." (PMID 32344689, 2020). "Acquired drug resistance to ALK inhibitors or sorafenib induces PD-L1 expression in cancer cells, which suggests the causality between drug resistance and increased PD-L1." (PMID 32024543, 2020). "Accumulating studies have demonstrated that acquired resistance to chemotherapeutic agents such as platinum, EGFR-TK inhibitors, and ALK inhibitors is associated with increased PD-L1 in cancer cells." (PMID 32024543, 2020). "When expanding our investigation of other cancer predisposition genes besides ALK and PHOX2B, we detect rare variants such as a nonsense mutation in BARD1 as well as missense variants in CHEK2, BRCA2, and WRN." (PMID 33384420, 2020). "In summary, miRNAs are modulators of crucial cancer-associated signaling pathways in ALK-positive ALCL." (PMID 31052302, 2019). "Alternatively, overexpressed or gain-of-function mutated dependence receptors can play a role in cancer as oncogenes, as shown for ALK." (PMID 30813562, 2019). "It was suggested that the 2nd and additional biopsies (including liquid biopsy) and analysis of ALK mutations would become more important when selecting optimal ALK-TKIs for cancers continuously acquiring mutations." (PMID 30404198, 2018). "In cancer development, however, ALK took the spotlight when it was discovered that the ALK gene is fused to echinoderm microtubule-associated protein like 4 (EML4) on chromosome 2 in NSCLC." (PMID 30404198, 2018). "ALK is mutated or aberrantly expressed in some cancers, notably in the form of the ALKATI variant, characterized by an alternative transcription initiation (ATI) site." (PMID 28968689, 2018). "An efficient strategy using cfDNA in cancer diagnostics, the development of more accurate and cost-effective tools to identify informative multiple secondary ALK mutations is clinically required." (PMID 30453899, 2018). "High response rates (60–70%) are achieved with the EGFR TKIs in EGFR-mutated cancers and ~60% of partial/complete responses with anaplastic lymphoma kinase (ALK) inhibitors (e.g., crizotinib) in patients with ALK translocations." (PMID 30087852, 2018). "This is complicated by the various alterations in ALK that are found in human cancers including fusions, point mutations and amplifications." (PMID 29455675, 2018). "The efficacy of ALK inhibitors in cells harbouring point mutations in ALK was first demonstrated in a screen of 602 cancer cell lines with TAE684, a highly selective compound previously shown to inhibit the NPM-ALK fusion oncoprotein in ALCL." (PMID 29642598, 2018). "The pathogenesis of several cancers is closely related to aberrant forms of ALK or aberrant ALK expression, including ALK fusion proteins, ALK-activated point mutations, and ALK amplification." (PMID 30400214, 2018).